CD44 (CD44 molecule (IN blood group))
Diseases named in the same sentence as CD44 in open-access papers (continued):
Sharing a sentence is not in itself a finding about the gene and the disease.
lupus nephritis (8 papers, 2012 to 2025). Glomerulonephritis in the context of systemic lupus erythematosus. "We investigated its role in kidney inflammation and fibrosis in a murine model of lupus nephritis (LN), and the clinico-pathological association of serum CD44 level in patients with biopsy-proven Class III/IV ± V LN." (PMID 39411720, 2024). "In lupus nephritis (LN), the presence of CD44 on tubular epithelial cells and infiltrating leukocytes is associated with increased inflammation and fibrosis." (PMID 41009438, 2025). "This idea is supported by the protective effects of CD44 inhibition in prolonged models of crescentic GN and lupus nephritis." (PMID 37494581, 2023). "The key role of this same CD44–hyaluronic acid interaction in T cell homing was demonstrated recently in lupus nephritis." (PMID 34793332, 2022). "HA is a ligand for CD44 and its levels have been reported increased in the sera and kidneys of patients and mice with active lupus nephritis." (PMID 31572382, 2019). "Through its interaction with CD44, HA regulates leukocyte infiltration, secretion of inflammatory mediators, and clearance of apoptotic cells processes that dictate the severity of lupus nephritis." (PMID 22900150, 2012). "In addition, CD44 has been demonstrated to be associated with the pathogenesis of crescentic glomerulonephritis, AKI, lupus nephritis and CsA-induced renal injury." (PMID 41301516, 2025). "Further research into the interaction of HA with other binding proteins will provide us with a better understanding of their roles in the pathophysiology of lupus nephritis and whether targeting HA or CD44 may serve as a novel therapeutic strategy." (PMID 22900150, 2012). "We and others have demonstrated that HA and CD44 expression is increased in the glomerular and tubulo-interstitial compartments of the kidneys, with predominant expression of HA and CD44 in the periglomerular area and in atrophic tubules of patients and mice with active lupus nephritis." (PMID 22900150, 2012).
malaria (8 papers, 2015 to 2024). Malaria is a serious and sometimes fatal disease caused by a parasite that commonly infects a certain type of mosquito which feeds on humans. "The increased CD44 expression in PbANKA-infected mice suggests that CD44 may also contribute to the recruitment of macrophages into the lung during malaria-associated ALI, which requires further investigation." (PMID 27554340, 2016). "Our data show that the 293-gp96-Ig-PfCA malaria vaccine induces a predominant population of liver-infiltrating CD44+CD62L-CD69+KLRG1low Trm cells in mice, characterized by an increased production of IFN-γ upon in vitro antigenic stimulation." (PMID 37056783, 2023). "CD44, CD36 and ICAM1 have been previously reported to play an important role in malaria pathophysiology." (PMID 38828264, 2024). "As IFN-γ-producing effector/effector memory cells play a key role in the induction and maintenance of long-term protection against malaria mediated by CD4+ T cells or CD8+ T cells, gated CD4+ and CD8+ splenocytes were analyzed for expression of CD62L and CD44." (PMID 37553591, 2023). "To better understand the mechanism of ALI in malaria infection, here we investigated the roles of galectin (Gal)-1, 3, 8, 9 and the receptors of Gal-9 (Tim-3, CD44, CD137, and PDI) in malaria-induced ALI." (PMID 27554340, 2016). "We demonstrated that interactions of Gal-9 and its receptors (Tim-3, CD44, CD137, and PDI) play a role in the development of ALI in PbANKA-infected mouse model, providing an important mechanism for severe malaria." (PMID 27554340, 2016).
metastatic prostate carcinoma (8 papers, 2012 to 2023). A carcinoma that arises from the prostate gland and has spread to other anatomic sites. "Recent studies have implicated CD147 and CD44 in the modulation of the Wnt/β-catenin pathway in metastatic prostate cancer, a property that is being investigated as a potential therapeutic strategy." (PMID 36498950, 2022). "We have presented evidence that integration of two different signaling pathways (CD44 and αvβ3) facilitate osteoclastogenesis and bone loss via a RUNX2/Smad5/RANKL axis in metastatic prostate cancer cells." (PMID 22966907, 2012).
non-alcoholic steatohepatitis (8 papers, 2015 to 2025). "In vivo studies in experimental models of non-alcoholic steatohepatitis assessing CD44 deficiency suggest that HA molecules exert modulatory actions on hepatic macrophages, including resident KCs and infiltrating monocyte-derived macrophages." (PMID 41155434, 2025). "Paradoxically, a prior study suggested that CD44 deficiency enhances M2 polarization in non-alcoholic steatohepatitis (NASH) in mouse models." (PMID 36276655, 2022). "CD44-deficient mice have markedly attenuated hepatitis in a mouse model of non-alcoholic steatohepatitis (NASH), induced by administration of a lithogenic diet." (PMID 25741341, 2015). "CD44 is a key marker for the hepatic inflammation and strongly up-regulated in non-alcoholic steatohepatitis (NASH) patients." (PMID 32471201, 2020). "CD44, is proved to be of great significance in non-alcoholic steatohepatitis." (PMID 33995497, 2021). "In addition, it has been reported that CD44 is a key player in non-alcoholic steatohepatitis (NASH)." (PMID 35087870, 2021).
periodontitis (8 papers, 2019 to 2025). An acute or chronic inflammatory process that affects the tissues that surround and support the teeth. "By comparing differentially expressed genes in neutrophils between the two groups, several inflammation‐associated genes, such as IL1B, CD44, CXCL8, and CCL4 were upregulated in the gingivae from patients with periodontitis versus healthy subjects." (PMID 37639212, 2023). "Of the population of CD4+ and CD8+ T cells that had infiltrated the inflamed gingiva, the percentage of CD44+ memory T cells was lower in periodontitis-induced obese mice treated with miR-25-3p inhibitor." (PMID 35069547, 2021). "Analyzing a subset of CD4+ and CD8+ T lymphocytes, we observed that the population of memory T cells (CD44+CD62L–) increased in the regional lymph nodes of HFD-fed mice with periodontitis, whereas the population of naïve T cells (CD44–CD62L+) decreased." (PMID 35069547, 2021). "Moreover, we found specific proteins - drivers or suppressors - associated with ferroptosis (SNCA, FTH1, HSPB1, CD44, and GCLC), revealing the co-occurrence of this specific type of regulated cell death during the clinical progression of periodontitis." (PMID 38802345, 2024). "CD44 plays a significant role in anoikis induction; therefore, the observed degradation of CD44 on gingival keratinocytes by gingipains could be one of the inducers of anoikis leading to a damage of the gingival epithelium during progression of periodontitis." (PMID 32411104, 2020). "In the context of periodontitis, Ptx3 was found in the HA-dependent pericellular matrix (PCM) of mouse pre-osteoblast cells, where it enhances HA synthesis and Cd44 expression, thereby strengthening the HA-Cd44 interaction." (PMID 41479916, 2025). "In the Pg sample, we observed interactions between ADM and CALCRL, which is related to periodontitis; EDA and EDA2R, which is related to ectodermal development; and SPP1 and CD44 and SPP1 and (ITGA4+ITGB1), which promotes phosphoprotein secretion and regulates bone salinization." (PMID 37287452, 2023). "A high expression of stem cell biomarkers (CD44, CD73, CD90, CD105, and CD146) suggests a regenerative potential of periodontal granulation tissue harvested from patients with periodontitis and might be an overlooked biological therapeutic factor." (PMID 36926181, 2023).
preeclampsia (8 papers, 2017 to 2025). Preeclampsia is a hypertensive disorder of pregnancy that is characterized by new-onset hypertension with proteinuria presenting after 20 weeks of gestation, and depending on mild or severe forms may initially present with severe headache, visual disturbances, and hyperreflexia. "At 20 weeks of gestation, a high plasma CD44/FKBPL ratio was independently associated with the 2.3-fold increased risk of preeclampsia (odds ratio = 2.3, 95% confidence interval [CI] 1.03-5.23, P = 0.04)." (PMID 32617576, 2021). "Our results show that the CD44/FKBPL ratio is associated with the risk of preeclampsia independently of established risk factors including age, BMI, MAP, and weight gain, from 20 weeks of gestation." (PMID 32617576, 2021). "Plasma FKBPL concentration was reduced at both 15 and 20 weeks of gestation whereas plasma CD44 concentration was increased at 20 weeks of gestation in a low-risk cohort of women who proceeded to develop preeclampsia." (PMID 32617576, 2021). "Recent studies show that FKBPL regulates inflammatory STAT3 signalling, via CD44 and NFkB, which are both implicated in preeclampsia." (PMID 33879252, 2021). "Using this cut-off point, a univariate logistic regression model demonstrated, that women with a CD44/FKBPL ratio above 143.6 or 155.1 had a 2.5- or 2.4-fold increased risk of developing preeclampsia later in pregnancy (P = 0.02, P = 0.03), respectively." (PMID 32617576, 2021). "The plasma CD44/FKBPL ratio could provide a novel risk stratification approach for preeclampsia at 20 weeks of gestation, capable of identifying women at high risk, who otherwise appear healthy." (PMID 32617576, 2021). "In comparison to the control group, patients with early-onset preeclampsia displayed a significantly elevated plasma FKBPL signal (approximately 20%), while preeclampsia samples demonstrated a significant decrease in CD44 signal strength (around 40%)." (PMID 39744682, 2025). "The biomarkers FKBPL and CD44 have been identified as potential indicators for predicting and diagnosing preeclampsia." (PMID 39744682, 2025). "FKBPL and CD44 plasma concentration or placental expression were determined in women pre- or postdiagnosis of preeclampsia." (PMID 32617576, 2021). "The combined effect of the CD44/FKBPL ratio and MAP (cut-off = 82.5 mmHg; AUC = 0.648, P = 0.004; sensitivity = 0.62, specificity = 0.59), on the risk of developing preeclampsia was investigated using multinomial logistic regression models." (PMID 32617576, 2021). "Statistical significance was maintained (P = 0.02) when the CD44/FKBPL ratio was adjusted for differences in gestational age between the preeclampsia and control groups, using logistic regression." (PMID 32617576, 2021). "At 20 weeks of gestation, a high CD44/FKBPL ratio and high MAP were associated with an approximately 4-fold increased risk of preeclampsia." (PMID 32617576, 2021). "In preeclampsia, FKBPL and its target protein, CD44, have demonstrated their predictive and diagnostic biomarker potential, likely reflective of the pathogenesis of preeclampsia and placental hypoxia." (PMID 34149611, 2021). "Consequently, this indicates that the CD44/FKBPL intensity ratio is considerably lower in cases of early-onset preeclampsia when compared to the control group." (PMID 39744682, 2025). "We demonstrated that FKBPL expression analyzed against its target, CD44, as a CD44/FKBPL ratio, could be used as a potential predictive and diagnostic tool for preeclampsia, although its role in the pathogenesis of preeclampsia requires further elucidation." (PMID 36652019, 2023). "However, the trend in FKBPL/CD44 expression levels is the same in placentae from Cohort 2 and plasma samples from Cohort 1, both of which are postdiagnosis of preeclampsia." (PMID 32617576, 2021). "The CD44/FKBPL ratio could also identify the cases of evolving preeclampsia through longitudinal changes potentially leading to early detection of this condition." (PMID 32617576, 2021).
preeclampsia (continued). "At 20 weeks of gestation, the CD44/FKBPL ratio in combination with mean arterial blood pressure (MAP) was capable of predicting a four-fold increased risk of preeclampsia in nulliparous pregnant women; most of the pregnancies in our cohort proceeded to develop late-onset preeclampsia." (PMID 32617576, 2021). "Both FKBPL and CD44 are regulated by hypoxia and appear to have key roles in the processes important for SUA remodeling preceding the onset of preeclampsia." (PMID 32617576, 2021). "The CD44/FKBPL ratio was also capable of diagnosing preeclampsia and was differentially expressed in placentae affected by preeclampsia." (PMID 32617576, 2021). "Human samples prediagnosis (15 and 20 weeks of gestation; n ≥ 57), or postdiagnosis (n = 18 for plasma; n = 4 for placenta) of preeclampsia were used to determine FKBPL and CD44 levels, compared to healthy controls." (PMID 32617576, 2021). "The CD44/FKBPL ratio was reduced in placenta and plasma following clinical diagnosis of preeclampsia." (PMID 32617576, 2021). "Placental expression of FKBPL, CD44, intercellular adhesion molecule (ICAM), and vascular cell adhesion molecule (VCAM) from women with preeclampsia were compared to their normotensive controls (matched for age, BMI, and gestational age)." (PMID 32617576, 2021). "In the future, CD44 and FKBPL plasma concentrations should be investigated in a larger cohort of patients using longitudinal plasma samples from all three trimesters and postdiagnosis of preeclampsia." (PMID 32617576, 2021). "Notably, hypoxia as a pro-angiogenic stimulus, which is present in the ischemic placenta in preeclampsia, led to a reduction in endothelial and trophoblast FKBPL protein and mRNA expressions and a concomitant increase in CD44 mRNA expression." (PMID 32617576, 2021). "Interestingly, in established preeclampsia, the CD44/FKBPL ratio showed an opposite pattern, suggesting that these potential longitudinal changes in CD44/FKBPL ratio from trimester 2 to 3 could reflect evolving preeclampsia and, therefore, could be explored for early diagnosis." (PMID 32617576, 2021).
prostate (8 papers, 2017 to 2025). "Our study suggests a pathogenic role for CD44 in LN through its ability to recruit B and T cells into the kidney and induction of kidney inflammation and fibrosis leading to kidney function deterioration." (PMID 39411720, 2024). "Reduced CD44 expression was also accompanied by a decrease in proteinuria, interstitial HA expression and mediators of kidney inflammation and fibrosis compared to Control IgG-treated mice." (PMID 39411720, 2024). "Here, we aimed to investigate the role of CD44 and the ligand, hyaluronan (HA), on chronic prostatitis/chronic pelvic pain syndrome (CP/CPPS) pathogenesis." (PMID 35693826, 2022). "We also analyzed CaOx crystal-binding molecules CD44 and annexin II because we previously reported that induction of these molecules is a key element to link CaOx microcrystal formation with nephrocalcinosis and kidney injury." (PMID 40221396, 2025). "Microarray analysis revealed that expression of genes related to the PI3K/AKT signaling pathway was elevated in sphere-cultured CD133+/CD44- prostate CSCs, and knockdown of phosphatase and tensin homolog (PTEN) stimulated sphere formation by inhibiting PI3K/AKT signaling." (PMID 35155201, 2021). "Hyaluronic acid (HA)/CD44 regulates Th1 differentiation by activating the Annexin A1-AKT-mTOR signaling pathway, promoting the pathogenesis of chronic prostatitis/chronic pelvic pain syndrome (CP/CPPS)." (PMID 37266437, 2023).
prostate adenocarcinoma (8 papers, 2013 to 2024). "Upregulation of CD44 expression by certain microRNAs can be utilized as a novel therapeutic agent against prostatic adenocarcinoma; if CD44 expression is found early, we can prevent the disease progression to advanced stages." (PMID 37461792, 2023). "Using microarray sections (two PR242a and one PR243 from Biomax) containing six cases of prostate adenocarcinoma and six adjacent normal prostate tissues with duplicate cores for each case, we performed an immunohistochemical analysis with antibodies to CD44-ICD." (PMID 33062960, 2020). "Significantly, these cultured human prostate adenocarcinomas also contained cells with stem-like properties as shown by expression of CD133, CD44, ALDH7A1, CK5/14 and α2β1 antigens." (PMID 27764770, 2016). "In human prostate, a minor subgroup of “stem” cells (CD44+, Oct4+) expresses EZH2 and has been proposed to represent a cell reservoir for prostatic adenocarcinoma initiation." (PMID 23675307, 2013).
salivary gland tumors (8 papers, 2011 to 2025). "Analysis of the expression of CD44 and its variant isoforms in salivary gland tumors has yielded different results depending on the type of tumor studied." (PMID 26821610, 2016). "Strong expression of ALDH1A1 and minimal CD44 staining was present in salivary gland tumors generated with ALDHhighCD44high cells." (PMID 40371051, 2025). "Two recent studies have reported positive tumor cell staining for ALDH and CD44 in malignant salivary gland tumors." (PMID 40371051, 2025). "In another study, the expression of CD44 was analyzed in benign and malignant salivary gland tumors." (PMID 39684268, 2024). "Our results establish the existence of T-ICs in murine salivary gland tumors, and suggest a potential molecular mechanism for CD44 upregulation." (PMID 21858056, 2011). "Using the established Pleomorphic Adenoma Gene-1 (Plag1) transgenic mouse model of a salivary gland tumor, we identified CD44high (CD44hi) tumor cells, characterized by high levels of CD44 cell surface expression, as the T-ICs for pleomorphic adenomas." (PMID 21858056, 2011). "Similarly, there was a positive correlation between CD44 and tumour grade in salivary gland tumours." (PMID 34944493, 2021). "Thus, CD44 protein expression was significantly upregulated in salivary gland tumor cells." (PMID 21858056, 2011). "Hematoxylin and eosin staining revealed a salivary gland tumor with poorly differentiated, solid phenotype with low ALDH1A1 and strong CD44, HLA and keratin-7 expression." (PMID 40371051, 2025). "The immunophenotype CD44+/CD24- was the most prevalent, appearing in 52,2% of salivary glands tumors." (PMID 23419168, 2013). "However, no study has reported a link among CD44 expression, other biomarkers, and the aggressiveness of salivary gland tumors." (PMID 35626430, 2022).
allergic asthma (7 papers, 2015 to 2025). A asthma with a basis in a pathological type I hypersensitivity reaction. "To investigate the relationship between CD4+CD44+ memory T cells and allergic asthma, we performed flow cytometry analysis on three different models." (PMID 39632661, 2024). "In a study using a murine model of allergic asthma it was shown that mammalian galectin-9 can modulate CD44-dependent leukocyte recognition of the extracellular matrix leading to a reduction in airway hyperresponsiveness." (PMID 36032131, 2022). "We also explore the mechanisms regulating these interactions, and highlight the importance of T helper type 2 (Th2) cell recruitment by CD44-HA interactions in the pathogenesis of acute allergic asthma in an experimental mouse model." (PMID 35069598, 2021). "Osteopontin, another major ligand of CD44, plays an important role in the pathogenesis of Th2 skewing witnessed in allergic asthma." (PMID 26999446, 2016).